TNFSF14 (TNF superfamily member 14)
Diseases named in the same sentence as TNFSF14 in open-access papers (continued):
Sharing a sentence is not in itself a finding about the gene and the disease.
tumor (continued). "For example, acting as a receptor for TNFSF14 or LTA, TNFRSF14 can stimulate downstream NF-κB signaling to promote NK cell and T-lymphocyte proliferation, IFN-γ production, and tumor cell clearance." (PMID 34858395, 2021). "With increased tumor PD-L1, expression of activation and cytotoxicity marker genes, including IFNG, TNFSF9, TNFSF14, CSF2, and IL2, were downregulated in both Tnull and TCR-TMART-1, consistent with results of cytokine secretion assays." (PMID 33754038, 2021). "Among these costimulatory molecules, LIGHT/TNFSF14 plays a key role in regulating T-cell function and promoting T-cell mediated anti-tumor immunity." (PMID 32310827, 2020). "These strategies have varied from use of the LTβR ligand LIGHT (TNFSF14) to adoptive transfer of DC expressing CCL21, and have shown efficacy in a number of diverse tumor models." (PMID 33013886, 2020). "These cells however overexpressed immune checkpoint inhibitory molecules, such as PD1, BTLA, TNFSF14 (LIGHT), and TIGIT, which are the sign of immune exhaustion or inhibition of tumor infiltrating lymphocytes." (PMID 30965637, 2019). "In contrast, tumor suppressive mediators made up most inversely correlated genes, e.g. CXCL10, CXCL11, IL15, TNFSF10/TRAIL, and TNFSF14/LIGHT." (PMID 29141914, 2018). "Ectopic delivery of LTα/β or LIGHT (aka TNFSF-14 or CD258) promotes PNAd+ HEV, CCL19/CCL21 production, massive naïve T cell infiltration, and (tumor-specific) cross-priming in the context of TLO structures." (PMID 24348473, 2013). "Similarly, the downregulation of CSF2, CXCR3, and TNFSF14 in PBMCs from CRC patients suggests a potential impairment in immune activation and anti-tumor responses." (PMID 40484866, 2025). "Some of the most widely used bacterial vectors are derived from Salmonella typhimurium, which can be modified to secrete LIGHT/TNFSF14, IL18, FASL and TRAIL cytokines, and when injected intravenously into laboratory animals, contribute to the tumor reduction in vivo." (PMID 38715617, 2024). "Recently, an engineered fusion protein, TIGIT-Fc-LIGHT, the linkage between the extracellular domain of TIGIT and the extracellular domain of TNFSF14, was reported to show anti-tumor activity in pre-clinical models, especially in those who were resistant to anti-PD-1 treatment." (PMID 38229100, 2024). "In addition, the expression of receptors, including TNFSF14, CD40, LTBR, and VTCN1, was elevated in LN-out tumor cells." (PMID 38519500, 2024). "BAD promotes cell death, and TNFSF14 protein stimulates the proliferation of T cells and trigger apoptosis of tumor cells—while TNFAIP8 acts as the negative mediator of apoptosis." (PMID 36839713, 2023). "The immune checkpoint TNFSF14 in Neutrophils, NK Cells, and Monocytes and BTLA in Treg Cells, Granulosa Cells, and B Cells interact with LTBR and TNFRSF14 in Cancer Cells to mediate cytotoxicity and promote tumor killing." (PMID 36401283, 2022). "High tumor expression of TNFRSF14 and CD160, but not TNFSF14, LTA, or BTLA, was associated with improved BLCA patient prognosis, suggesting that the TNFRSF14–CD160 interaction, like KLRK1, is a prominent pathway of NK cell tumor surveillance in BLCA." (PMID 34858395, 2021). "In this study, we armed oncolytic MYXV with the murine Light gene, encoding mouse tumor necrosis factor ligand superfamily member 14 (TNFSF14, synonym: LIGHT), which was designed to promote the influx of T lymphocytes into the tumor and thus intensify the immune response directed against the tumor." (PMID 33808692, 2021). "TNFSF14 induces the noncanonical NF-κB pathway in certain types of cancer cells to promote tumor development." (PMID 32983989, 2020). "Furthermore, ANGPLT4 played a critical role in regulating tumor cell proliferation and angiogenesis, possibly by regulating STC1, EPHA3 and TNFSF14 genes." (PMID 28903395, 2017).
tumor (continued). "Some studies suggest that TNFSF14 can sensitize tumors to IFN-γ-mediated apoptosis, induce the normalization of tumor vasculature, stimulate effector cell functions, and promote the infiltration of CD8 + T cells into tumors, which helps establish long-term anti-tumor memory." (PMID 40072746, 2025). "Based on currently available evidence, LIGHT (TNFSF14; a member of the tumor necrosis factor (TNF) receptor superfamily) has a central role in regulation of antitumor immunity by co-stimulating the proliferation of T cells and activating apoptosis of different tumor cells." (PMID 34249257, 2021). "Importantly, SPC25 showed a significant positive correlation with COAD expressing many immune checkpoint genes, especially NRP1, CD276, TNFSF14, and other important immunotherapeutic targets, which may also be closely related to the immune escape mechanism of ACC tumor cells." (PMID 38605119, 2024). "Further, expression of lymphotoxin-A and tumor necrosis factor superfamily-14 (TNFSF14/LIGHT) by NK and complementary TNFRSF1B and TNFRSF14/HVEM (herpes virus entry mediator) by CTL may serve as a substrate for CTL–NK compartmentalization in tumors or tumor-draining lymph nodes." (PMID 31456803, 2019). "In contrast, CDH18 showed negative correlations with TNFSF14, TNFSF15, PDCD1, TNFRSF14, and CD44, genes reported to play critical roles in tumor inhibition." (PMID 40017628, 2025).
cancer (78 papers, 2014 to 2026). A tumor composed of atypical neoplastic, often pleomorphic cells that invade other tissues. "In contrast, a uniform negative association with PEBP1/STK11 co-expression was found in most of the genes encoding TNF ligands (ENFSF13B, TNFSF4, TNFSF9, TNFSF14, TNFSF18, and TNFSF15) in almost all cancer types." (PMID 40806276, 2025). "For instance, a recent MyxV bioengineered to express TNF and TNFSF14 demonstrated strong responses as a stand-alone cancer therapy and when combined with immunotherapy in several cancer models." (PMID 37835397, 2023). "The TNFSF14 expression was largely found on immune cells such as activated T cells, NK, and immature DCs as well as several cancer cells." (PMID 37024802, 2023). "In most cancers, as classical immunostimulators, CD40LG and TNFSF14 were negatively associated with SLC3A2." (PMID 35992269, 2022). "Specifically, TNFSF13 and TNFSF14 can increase the effects of immunotherapy by facilitating immune cell mobilization into the cancer." (PMID 35432372, 2022). "Our present studies further reinforce the relationship of TNFSF14 with cancer, immune characteristic, and survival status." (PMID 34925447, 2021). "Of interest, the integrative analyses highlighted TNFSF14 as one of the key functional modulators within the CIK-EIG-associated immune landscape, showing a strong association with cytotoxic immune signaling and cancer-immunity cycle activity." (PMID 42159775, 2026). "There remains ongoing debate concerning the relationship between TNFSF14 and cancer." (PMID 40072746, 2025). "In this current study, we report that MYXV armed with murine LIGHT (TNF Superfamily member 14: TNFSF14) is also a positive hit in the K7M2-luc lung metastatic osteosarcoma model but possesses even more potent anti-cancer activities against advanced later-stage disease than vMyx-hTNF." (PMID 35053501, 2022). "We identified multiple TNF superfamily members with direct apoptotic effects on cancer cells, including TNFSF10 (TRAIL), TNFSF14 (LIGHT), TNFSF15 (TL1A), and LTA." (PMID 40564222, 2025). "Tumor necrosis factor superfamily member 14 (TNFSF14; also known as LIGHT) acts as an enhanced cancer immunotherapeutic agent to fight cancer." (PMID 37511932, 2023). "Two immunomodulators, TNFSF14 and TNFRSF25, were found to regulate GSDMB gene expression in cancers." (PMID 37064151, 2023). "In murine cancer models, TLS formation has been successfully triggered using its two ligands, LTα1β2 and LIGHT/TNFSF14." (PMID 37954592, 2023). "According to the correlation analysis between SRSF3 and immune checkpoint gene expression, it can be found that SRSF3 is closely related to TNFSF14, TNFRSF14, TNFRSF25, CD276, NRP1, VSIR in a variety of malignant tumors (P <0.05)." (PMID 35494088, 2022). "In various types of cancer, findings between NNMT and immunostimulator gene expression showed a high connection (p < 0.05), including TNFSF13B, TNFRSF8, TNFSF14, IL6, IL2RA, CD80, CD27, and CD86." (PMID 36386816, 2022). "In most cancers, CD86, TNFSF14, KLRK1, CD48, CD40LG, CD28, C10orf54, ENTPD1, CXCL12, and POLD2 are negatively correlated (p < 0.05)." (PMID 36081989, 2022). "The associations of P4HA1 expression with LAG3, ICOS, CTLA4, CD48, TNFSF14, and CD27 expression were inconsistent among cancer types." (PMID 35812752, 2022). "Concerning immune checkpoints, highly expressed TNFSF14 in Neutrophils, NK Cells, and Monocytes, BTLA in Treg Cells, Granulosa Cells, and B Cells, together with LTBR and TNFRSF14 in Cancer Cells, interact to help kill Cancer Cells." (PMID 36401283, 2022). "TNFSF14 is also known as LIGHT, which has been studied at preclinical level for more than 10 years and has shown the prospect of strengthening cancer immunotherapy." (PMID 33708242, 2021). "For example, SFRP4, WNT11, FZD2, MYC were highly expressed in cancer tissues which represent the Wnt pathway was activiated and BCL2A1, ICM1, TNFSF14 in NF-κB pathway were highly expressed as well." (PMID 25928635, 2015).
cancer (continued). "LIGHT (TNFSF14) binds to TNFRSF14 (HVEM) and LTβR on cancer cells, promoting apoptosis." (PMID 40564222, 2025). "And the glycogen riskScore was significantly positively related with immunoinhibitors TGFB1, ICAM1 and CD276, and showed significantly negative relationship with immunostimulators TNFSF14 across pan-cancer." (PMID 39895799, 2025). "In addition, five PRIs (HHLA2, IL2RA, TNFRSF18, TNFSF14, and CTLA4) included in the signature were regarded as potential PLAUR-related biomarkers in KIRC, which were studied in other cancers including KIRC based on the current literature." (PMID 36052236, 2022). "Here, we report that the non-canonical inducer TNFSF14/LIGHT leads to HIF induction and activation in cancer cells." (PMID 30096845, 2018).
infection (25 papers, 2009 to 2026). The state of being infected such as from the introduction of a foreign agent such as serum, vaccine, antigenic substance or organism. "Among the top downmodulated proteins, TNFSF14 is a ligand for a member of the tumour necrosis factor receptor superfamily predominantly expressed in the spleen and implicated in the herpesvirus entry into cells during infection." (PMID 38468336, 2024). "Depending on the cell type, pathogen interaction, and receptor availability, TNFSF14 can influence cell survival, (re)programming of the cell profile, immune response establishment, and infection memory." (PMID 41252214, 2026). "Only six mediators, ADA, CXCL1, CCL20, MCP-3, PD-L2, and TNFSF14, differed between the “infection-free” and actively infected groups." (PMID 41387890, 2025). "Levels of IL-17A and TNFSF14 are enhanced early after infection and gradually increase until late time points." (PMID 35479098, 2022). "We found that the expression of eight genes, including Il18, Il36b, Il17rc, Tnfsf10, Tnfsf11, Tnfsf14, Tnfsf15, and Il1a, were closely correlated with the severity of HAdV-55 infection." (PMID 30787914, 2019). "Aberrant release due to dysregulated neutrophil activation could offer an alternative explanation for the abundance of TNFSF14 upon severe infection." (PMID 41252214, 2026). "In the study, we showed increased circulating concentrations of 47 inflammatory proteins in patients with severe infection compared to healthy controls, with the most robust increase in the circulating concentration observed for TNFSF14, OSM, CCL23, IL-6, and HGF." (PMID 36209073, 2022). "Notably, H. felis infection significantly increased Tnfsf14 expression in the stomach of Myd88−/− mice, while only a slight increase was detected in WT animals after 25 weeks of infection." (PMID 31065023, 2019). "In the absence of infection, CF-TG cells constitutively exhibited an inflammatory signature, including genes that encode molecules such as IL-1α, IL-β, IL-32, TNFSF14, LIF, CXCL1 and PLAU." (PMID 19399182, 2009). "Early infection analysis showed eight markers that were elevated (padj<0.05) in the early infection group compared to the unexposed group, namely TGF-α, HGF, FGF-19, TNFSF14, TRAIL, RAGE-binding protein EN-RAGE, uPA and IL18R1." (PMID 41510260, 2025). "LIGHT (TNFSF14) is a member of the TNF superfamily involved in inflammation and defence against infection." (PMID 21998581, 2011).
liver (3 papers, 2022 to 2023). "Mouse studies have also shown that deficiency in TNFSF14 improves liver glucose tolerance and reduces liver inflammation and non-alcohol fatty liver." (PMID 35843982, 2022).
immune diseases (1 paper, 2025). "TNFSF14, an essential member of the TNF superfamily, was recently identified as a vital component of several immune diseases." (PMID 40768619, 2025).
inflammatory myopathies (1 paper, 2025). "Several tumor necrosis factor (TNF) superfamily genes (TNFSF8, LTB, TNFSF12, TNFSF13B, TNFSF14, TNFSF13, EDA) were upregulated, with LTB and EDA reaching higher levels than in other inflammatory myopathies." (PMID 41441888, 2025).
skin disorder (1 paper, 2025). Any deviation from the normal structure or function of the skin or subcutaneous tissue that is manifested by a characteristic set of symptoms and signs. "Increasing evidence regarding several inflammatory diseases suggests that TNFSF14 signalling dysregulation is a critical disease‐driving mechanism, especially in skin disorders." (PMID 40768619, 2025). "In recent years, TNFSF14 has attracted more attention as a potential enhancer in some skin disorders." (PMID 40768619, 2025).
TNFSF14 also shares sentences with these, for which no sentence is quoted: rheumatoid arthritis (8 papers); cardiovascular disease (6); colorectal cancer (6); inflammation (6); inflammatory bowel disease (6); Crohn disease (5); Insulin resistance (5); non-alcoholic fatty liver disease (5); idiopathic pulmonary fibrosis (4); lung disease (4); prostate tumor (4); chronic kidney disease (3); eosinophilic esophagitis (3); fibrosarcoma (3); Hyperinsulinemia (3); kidney injury (3); osteoporosis (3); systemic sclerosis (3); Acute hepatitis (2); acute myocardial infarction (2); airway hyperresponsiveness (2); alkaptonuria (2); allergic asthma (2); brain tumor (2); cervical cancer (2); Chronic colitis (2); chronic obstructive pulmonary disease (2); Glucose intolerance (2); interstitial lung disease (2); ischemic stroke (2).
A further 96 diseases each share a sentence with TNFSF14 in 2 papers or fewer.